LGI1 (leucine rich glioma inactivated 1)
Diseases named in the same sentence as LGI1 in open-access papers (continued):
Sharing a sentence is not in itself a finding about the gene and the disease.
encephalitis (continued). "Herein, we report, to our knowledge, the first case of a 65-year-old Chinese female presenting with two rare coexisting autoimmune syndromes: anti-LGI1 and anti-mGluR5 encephalitis." (PMID 36316880, 2022). "And indeed, this has been found to be the main effect in many IgG4-AID such as MuSK-MG, pemphigus vulgaris or anti-LGI1 encephalitis." (PMID 35401530, 2022). "Third, anti-NMDA receptor encephalitis is the most common autoimmune encephalitis; however, the antibody most frequently detected was the anti-LGI1 antibody and only one patient tested positive for the anti-NMDA receptor antibody during this study." (PMID 36188368, 2022). "Two biological siblings who worked in different regions were successively diagnosed with anti-LGI1 encephalitis in their middle age." (PMID 35493840, 2022). "We found anti-NMDAR encephalitis patients tended to have a poor first-line treatment response, while anti-LGI-1 encephalitis patients tend to have a good response." (PMID 35493830, 2022). "Among these patients, 40 had anti-NMDAR encephalitis, 36 had anti-LGI1 encephalitis, and 24 had anti-GABABR encephalitis." (PMID 35320933, 2022). "Patients with anti-LGI1 encephalitis who presented with cognitive impairments had significantly higher mRS scores on admission (p < 0.001) and at the 6-month follow-up examination (p = 0.018) than those without cognitive impairment symptoms." (PMID 36685530, 2022). "Patients with anti-LGI1 encephalitis had significantly higher CHI3L1 levels in the serum and CSF than controls." (PMID 36685530, 2022). "FBDS is a unique type of seizure and was only observed in patients with anti-LGI1 encephalitis, which was more frequently reported than other seizure types." (PMID 35281052, 2022). "Very recently, cloned recombinant human antibodies isolated from cerebrospinal fluid of three patients with the IgG4-AID anti-LGI1 encephalitis were analysed." (PMID 35401530, 2022). "For example, brain MRI shows unilateral or bilateral mesial temporal lobe hyperintensities in most cases of anti-LGI1 encephalitis; however, it can be normal in up to 25% of patients." (PMID 36672553, 2022). "Although it can be a paraneoplastic phenomenon, anti-LGI-1 encephalitis is mostly unrelated to tumors." (PMID 36348436, 2022). "Anti-GABABR encephalitis is the third most frequent AE after anti-N-methyl-D-aspartate receptor (anti-NMDAR) encephalitis and anti-leucine-rich, glioma-inactivated 1 receptor (anti-LGI1) encephalitis." (PMID 36091075, 2022). "Subsequently, increasing subtypes of antibody-mediated encephalitis such as leucine-rich glioma inactivated 1 (LGI1) encephalitis and γ-aminobutyric acid type B receptor (GABABR) encephalitis have been discovered." (PMID 35844590, 2022). "This is in accordance with a previous study that focused on disease outcome, which found that anti-LGI-1 encephalitis patients responded better to treatment and had a relatively better prognosis than anti-NMDAR encephalitis patients." (PMID 35493830, 2022). "Among these patterns of PET signals, if the one related to anti-LGI1 encephalitis metabolic abnormality is relatively strong, it will be visible in PET images (i.e., CD patient)." (PMID 35711267, 2022). "One study demonstrated that the prognosis of anti-LGI1 encephalitis patients with hyponatremia is poor." (PMID 36685530, 2022). "In the group of 1 patient with anti-LGI1 encephalitis, autoantibodies were detected in both serum and CSF." (PMID 35874583, 2022). "In the retrospective cohort study, we consecutively enrolled patients with anti-N1MDAR, anti-GABABR and anti-LGI1 encephalitis between March 2015 and November 2021." (PMID 35757705, 2022). "Patients with anti-NMDAR-encephalitis show a much higher median mRS at 3 months compared to patients with anti-LGI1/CASPR2-encephalitis." (PMID 34093529, 2021).
encephalitis (continued). "Patients with anti-LGI1 encephalitis present with progressive memory alteration, psychiatric manifestation and seizures, suggesting the involvement of the limbic system." (PMID 34616389, 2021). "In conclusion, hippocampal and basal ganglia hypermetabolism co-existing with neocortical hypometabolism is a common metabolic abnormality in anti-LGI1 encephalitis." (PMID 34616389, 2021). "Continuous insomnia was more common in patients with anti-CASPR2 encephalitis than with anti-LGI1 encephalitis." (PMID 34421519, 2021). "Antibody positivity persisted in 11/20 (55%) of repeatedly tested patients (seven anti-NMDAR, three anti-GABABR and one anti-LGI1 encephalitis patients)." (PMID 33767656, 2021). "Brain 18F-fluorodeoxyglucose positron emission tomography (FDG PET) is a sensitive technique for assisting in the diagnosis of patients with anti-leucine-rich glioma-inactivated 1 (LGI1) antibody encephalitis." (PMID 34616389, 2021). "Several recently described encephalitides (such as NMDAR, LGI1, and CASPR2 encephalitis) have been shown to be secondary to the pathogenic effect of autoantibodies binding to extracellular epitopes of neuronal cell surface proteins." (PMID 33935958, 2021). "Anti-LGI1 (leucine-rich glioma-inactivated 1) encephalitis is a newly discovered autoimmune encephalitis and a relatively common cause of limbic encephalitis." (PMID 34975858, 2021). "The most characteristic seizures are facio-brachial dystonic seizures (FBDS), which are characteristic of anti-LGI1 encephalitis, and these are observed in approximately half of the patients." (PMID 34616389, 2021). "RBD, periodic limb movements in sleep (PLMS) and obstructive sleep apnea were also observed in anti-LGI1 encephalitis." (PMID 34421519, 2021). "We do not discuss this substantial topic comprehensively here but rather we focus on special considerations relevant to the two most common forms of autoimmune encephalitis: NMDAR-antibody and LGI1-antibody encephalitis." (PMID 34108243, 2021). "Episodes can recur numerous times a day and are considered pathognomic of anti-leucine-rich glioma inactivated 1 (LGI1) encephalitis." (PMID 33935958, 2021). "Overall, the implications are important given that 1) anti-LGI1 encephalitis is the most common encephalitis in adults, but up to 13% develop cognitive impairment without criteria of encephalitis." (PMID 34267758, 2021). "Limbic encephalitis is frequently seen in autoimmune encephalitis, such as anti-NMDAR, GABAB-R, CASPR2, LGI1, and AMPAR encephalitis, suggesting common mechanisms underlined." (PMID 34915865, 2021). "Previous publications have reported of FBDS as a typical symptom of anti-LGI1 encephalitis, often occurring a few weeks before onset of cognitive deficit in 26–71% of patients." (PMID 33767656, 2021). "This 18F-FDG PET study focused on four patients with anti-LGI1 encephalitis through SPM analysis, and discovered the topography of anti-LGI1 encephalitis was partly consistent with the present study." (PMID 34616389, 2021). "In a second series of 38 patients with anti-LGI1 encephalitis, CSF was available for testing in 17 patients and only 9 (53%) were positive whereas all sera tested positive on the commercial IIFA." (PMID 34267758, 2021). "Twenty‐nine patients had anti‐NMDAR encephalitis (16 female and 13 male), 13 had anti‐GABABR encephalitis (4 female and 9 male), and 14 had anti‐LGI1 encephalitis (7 female and 7 male)." (PMID 33683811, 2021). "Anti-LGI1 encephalitis, also quite frequent, is characterized by a movement disorder that is almost pathognomonic, i.e., faciobrachial dystonic seizures." (PMID 34925200, 2021). "More distinct scores rather than the mRS are necessary to differentiate potential neurological improvements in patients with anti-LGI1-/CASPR2-encephalitis." (PMID 34093529, 2021).
encephalitis (continued). "There was documented response to immune therapy in 71.4% of cases in the anti-NMDA-receptor encephalitis subgroup, 71.4% in the anti-glycine-receptor subgroup and 87.5% in the anti-LGi1 subgroup." (PMID 33692738, 2021). "Based in a tertiary epilepsy center, this study retrospectively analyzed the clinical characteristics of 45 patients with anti-LGI1 encephalitis and followed them for an average of 32.8 months." (PMID 34168612, 2021). "The present study aimed to determine the brain common patterns of glucose metabolism changes in a relatively large sample of patients with anti-LGI1 encephalitis using Statistical Parametric Mapping (SPM) analysis." (PMID 34616389, 2021). "Anti-LGI1 encephalitis is an autoimmune encephalitis with antibodies against leucine-rich glioma-inactivated 1 (LGI1), first described in 2010." (PMID 33519701, 2021). "Clinical characteristics and potential mechanisms of anti-LGI1 encephalitis still need further elucidation." (PMID 34975858, 2021). "This explains amnesia in anti-AMPAR encephalitis patients and provides insights into the symptomatic overlap with LGI1 encephalitis, as LGI1-ADAM22 complex interacts with PSD95 and stabilizes AMPARs in the postsynaptic membrane." (PMID 34915865, 2021). "Such analysis showed that the SII had good predictive value for NMDAR antibody encephalitis, anti-LGI1 encephalitis, and other types of AE." (PMID 34675864, 2021). "When considering anti-LGI1 encephalitis has many phenotypes, including FBDS, grand mal seizures, focal aware motor seizures (FAMS), focal impaired awareness (FIAS) as well as hyponatremia." (PMID 34616389, 2021). "Our patient had anti-LGI-1 antibody encephalitis characterized by a constellation of faciobrachial dystonic seizures, memory loss, emotional lability, and psychiatric disturbances." (PMID 34437034, 2021). "In our cohort, the sex ratio and age structure of the anti-LGI1 encephalitis patients were both similar to previous studies; that is, it usually affects middle-aged or older people and is more common in males." (PMID 34168612, 2021). "A prospective study of nine patients with anti-LGI1 encephalitis also revealed the beneficial effect of early immunotherapy." (PMID 33767656, 2021). "The groupwise analysis revealed that patients with anti-LGI1 encephalitis had left hippocampal hypermetabolism and hypometabolism in almost all neocortical regions." (PMID 34616389, 2021). "Randomized placebo-controlled trial in LGI1 (leucine-rich glioma-inactivated 1) – positive encephalitis patients reported a major benefit regarding cognition and seizures after taking IVIGs compared to placebo treatment in 6/8 (75%) patients." (PMID 33584385, 2021). "In the group with anti‐LGI1 encephalitis, FBDS (42.9%, n = 14) was the most commonly observed seizure type and was only observed in this group." (PMID 33683811, 2021). "This single-center study was conducted in a cohort of patients with anti-LGI1 encephalitis to investigate the factors related to their functional recovery." (PMID 34975858, 2021). "Dozens of clinical and subclinical seizures were detected in the long‐range video EEG recording of an anti‐LGI1 encephalitis patient with focal aware motor seizures (A)." (PMID 34291554, 2021). "The present study revealed that the topography of anti-LGI1 encephalitis characterized by the hypermetabolism of the hippocampal and basal ganglia associated with the hypometabolism of the cortical areas." (PMID 34616389, 2021). "The prominent clinical feature of anti-LGI1 encephalitis is drug-resistant epilepsy, but most patients respond well to first-line immunotherapy plus anti-epileptic drugs (AEDs) and can gradually discontinue medication after their condition has been relieved." (PMID 34168612, 2021). "Sixty-seven patients (38 males, 29 females, average age 58.5 ± 13.9 years) diagnosed with anti-LGI1 encephalitis were enrolled." (PMID 34975858, 2021).
encephalitis (continued). "In accordance with previous publications of other series, the most common autoimmune encephalitis type was anti-NMDAR encephalitis, followed by anti-LGI1 encephalitis." (PMID 33767656, 2021). "In a retrospective study of anti-LGI1 encephalitis patients, CSF pleocytosis was identified in 23% of patients." (PMID 33767656, 2021). "Subcortical hypermetabolism associated with cortical hypometabolism presented with a common metabolic pattern in patients with anti-LGI1 encephalitis in the present study." (PMID 34616389, 2021). "Anti-neuronal IgG4-AID include MuSK myasthenia gravis, LGI1- and Caspr2-encephalitis and autoimmune nodo-/paranodopathies (CNTN1/Caspr1 or NF155 antibodies)." (PMID 35095860, 2021). "Among the 48 patients of anti-LGI1 encephalitis, 10 patients had prodrome, such as fever (n = 2), headache (n = 2), dizziness (n = 8), and fatigue or drowsiness (n = 2)." (PMID 35095744, 2021). "At present, the initial diagnosis of anti-LGI1 encephalitis is mainly based on the clinical manifestations, MRI, and antibody testing." (PMID 34616389, 2021). "By applying next-generation sequencing of CSF and PB B cell repertoires, one study found indirect evidence for a CNS-based antigen-driven response in six patients with LGI1 antibody encephalitis." (PMID 34679570, 2021). "Recently, a retrospective study based on PSG found that patients with anti-LGI1 encephalitis demonstrated a decrease in total sleep time, sleep efficiency, N3 sleep and REM sleep." (PMID 34421519, 2021). "In patients with anti-LGI1/CASPR2-encephalitis, treatment studies should focus on specific symptoms, e.g. seizures and cognition, or use more distinctive clinical scores like the Clinical Assessment Scale in Autoimmune Encephalitis (CASE)." (PMID 34093529, 2021). "This retrospective study enrolled 25 patients with anti-LGI1 encephalitis, who were admitted in Beijing Tiantan Hospital between September 2014 and July 2019." (PMID 34616389, 2021). "The next most common subtypes were fourteen cases of anti-glycine-receptor related neurological disease and eight cases of anti-LGi1 encephalitis." (PMID 33692738, 2021). "Autoantibody-mediated diseases, such as neuromyelitis optica spectrum disorder and LGI1 / NMDAR encephalitis, also show features of a CSF-specific B cell maturation and clonal connectivity with peripheral blood." (PMID 34679570, 2021). "Of the 67 patients included in the study, 42 had anti-LGI1 encephalitis, 13 anti-NMDA-R encephalitis, 8 anti-GABA-B-R encephalitis, and 4 anti-CASPR-2 encephalitis." (PMID 34546417, 2021). "Consistently, the literature points out that FBDS, known as a unique feature of anti‐LGI1 encephalitis, is more frequently encountered than other seizure types." (PMID 33683811, 2021). "Anti-leucine-rich glioma-inactivated 1 (LGI1) encephalitis is the most common limbic encephalitis with antibodies targeting neuronal surface antigens." (PMID 34616389, 2021). "Cranial MRI scans were performed in all patients; among them, 15 (33.3%) patients showed normal or nonspecific changes, and 30 (66.7%) patients showed specific changes related to anti-LGI1 encephalitis." (PMID 34168612, 2021). "The anti-N-methyl-D-aspartate receptor (NMDAR) encephalitis is the most common form of AE and the anti-leucine-rich glioma-inactivated 1 (LGI1) AE the second most common form." (PMID 34749759, 2021). "Of those, 28% had developed subtle seizures which were missed in the first weeks of disease onset; the most subtle seizures were seen in anti-LGI-1 encephalitis." (PMID 34546417, 2021). "Although CSF LGI1 antibodies are detected in around 90% of patients, there is an infrequent association with CSF lymphocytosis and OCB in LGI1 encephalitis." (PMID 34679570, 2021). "Here, 45 anti-LGI1 encephalitis patients were enrolled from our tertiary epilepsy center, and they were all followed up for at least 12 months." (PMID 34168612, 2021).
encephalitis (continued). "In this context, the anti-N-methyl-d-aspartate receptor (NMDAR) and leucine-rich, glioma-inactivated 1 (LGI1) autoantibody-mediated encephalitis is one of the best-characterized disease entities." (PMID 34679570, 2021). "Third, eight patients with anti-LGI1 encephalitis in the present study were treated with steroids within 24 hours of the initial brain 18F-FDG PET." (PMID 34616389, 2021). "The current study investigated brain MRI results of 76 patients with anti-LGI1 encephalitis and explored their clinical relevance." (PMID 33510707, 2020). "After the diagnosis of probable chronified anti-LGI1 encephalitis was made, two glucocorticoid pulse treatments were performed, which led to a slight improvement of mood and neurocognitive deficits." (PMID 32560097, 2020). "In LGI1 encephalitis, most patients have a chronic cognitive impairment, with memory predominantly affected but deficits of attention and executive function also reported." (PMID 32873782, 2020). "The MMSE and MoCA-B scales can be used to evaluate cognitive function in patients with anti-LGI1 encephalitis." (PMID 33162923, 2020). "We found PSG parameters did not change with frequencies of RWA/RBD, PLMS, FBDSs, or epileptiform discharges in patients with LGI1-Ab encephalitis." (PMID 32849186, 2020). "It is possible that the outgrowth of this pathogen is exclusive for anti-LGI1 encephalitis and serves as a potential biomaker for this disorder." (PMID 33193049, 2020). "Twenty-one PSG recordings from patients with LGI1-Ab encephalitis demonstrated a decrease in total sleep time (TST) (median 365.5, range 184.5–495.5 min), sleep efficiency (70.0%, 47–92%), N3 sleep (9.7%, 0–32.9%), and REM sleep (9.9%, 0.4–27.9%)." (PMID 32849186, 2020). "The results showed that anti-LGI1 encephalitis was characterized by cognitive impairment, faciobrachial dystonic seizures, hyponatremia, and psychiatric symptoms." (PMID 33193049, 2020). "Anti-LGI1 encephalitis typically evolves and predominately affects middle-aged and elderly males over 50 years old." (PMID 33162923, 2020). "Numerous case reports have illustrated the potential for antibodies to produce a phenocopy of established dementia syndromes, with misdiagnoses seen in cases of both NMDAR and LGI1 encephalitis mimicking atypical neurodegenerative dementias." (PMID 32873782, 2020). "The overall composition of microbial composition in the patient group was distinct from that in HCs, which again suggests an abnormal gut status in anti-LGI1 encephalitis." (PMID 33193049, 2020). "The three patients were diagnosed as anti-LGI1 encephalitis at 4, 5, and 9 months after onset and then immunotherapy." (PMID 33162923, 2020). "Cognitive impairment is one of the most common manifestations of anti-LGI1 encephalitis, with the main prominent being acute or subacute short-term loss." (PMID 33162923, 2020). "FBDS is a distinctive manifestation of anti-LGI1 encephalitis and was presented in 67% of the patients in this study." (PMID 33193049, 2020). "The clinical features along with MRI findings of FLAIR intensity signals in bilateral temporal lobes and positive LGI1 antibody in serum lead to the diagnosis of anti-LGI1 encephalitis in our patient." (PMID 32827010, 2020). "The results showed that within-sample microbial diversity reduced in the anti-LGI1 encephalitis patients." (PMID 33193049, 2020). "Consistent with previous reports, we found that RBD and PLMS were more common in LGI1-Ab encephalitis than in Caspr2-Ab diseases." (PMID 32849186, 2020). "In anti‐LGI1 encephalitis, the most commonly recorded findings were hypermetabolism in the basal ganglia, amygdala, and cortex." (PMID 32783406, 2020). "Anti‐LGI1 encephalitis has a low tumor concurrence rate of less than ten percent, the majority being thymomas." (PMID 32783406, 2020). "MRI abnormalities in anti-LGI1 encephalitis are most common in MTL and basal ganglia with T2/FLAIR hyperintensity." (PMID 33380947, 2020).